SNAI1 (snail family transcriptional repressor 1)
Diseases named in the same sentence as SNAI1 in open-access papers (continued):
Sharing a sentence is not in itself a finding about the gene and the disease.
breast cancer (continued). "Conversely, in PBMCs, NRP-1 and its interacting molecules SEMA4A and SNAI1 are significantly downregulated in breast cancer patients compared to healthy controls, indicating a protective role." (PMID 28607365, 2017). "It has been known that TNF-α promotes EMT by up-regulating transcription factors such as Twist1/2, Snai1/2 and Zeb1/2 in renal cell carcinoma, breast cancer cell and colon cancer cell." (PMID 28550311, 2017). "We first tested miR-182 expression in different breast cancer cell lines with SNAI1 overexpression, and found that miR-182 decreased in all these cell lines." (PMID 27894095, 2017). "Until now, the overexpression of SNAI1 has been extensively evaluated in different human cancer tissues and cell lines, particularly colon cancer 22, gastric cancer 23, breast cancer 24, and ovarian cancer." (PMID 27239445, 2016). "EMT induction through the overexpression of snail homolog 1 (SNAI1) in MCF7 breast cancer cell line led to autophagy induction through the upregulation of BECN1." (PMID 27917371, 2016). "miR-661 is shown to regulate Nectin-1 and StarD10 in the disassembly of epithelial cell junctions in SNAI1-expressing breast cancer cells." (PMID 26512777, 2015). "Taken together, our finding has uncovered another mode of regulation for E-cadherin transcription in breast cancer, one that is based on direct antagonism of the SNAI1 protein by DACH1." (PMID 25775416, 2015). "DACH1 inhibited the transcriptional activity of SNAI1, leading to the activation of E-cadherin in breast cancer cells." (PMID 25775416, 2015). "We also proposed that DACH1 interacted with SNAI1 at the E-box of E-cadherin promoter and inhibited the transcriptional activity of SNAI1, leading to the activation of E-cadherin in breast cancer cells." (PMID 25775416, 2015). "Both in mouse mammary tumors and in human breast cancers, we observed elevation of Vim, Cdh2 (N-cadherin), Snai1 and Twist1 and downregulation of Cdh1 (E-cadherin) and Ocln." (PMID 25217618, 2014). "Consistently with this observation, SNAI1 is commonly induced in human breast carcinoma cell lines (FC>10, 63.6%, n = 11) as compared to HMEC-hTERT cells." (PMID 24638100, 2014). "MDA-MB-231 cells are metastatic breast cancer cells that express multiple zinc finger transcriptional repressors, including Snai1, Snai2, Zeb1 and Zeb2, all of which can bind Eboxes in the E-cadherin promoter and regulate EMT." (PMID 22393397, 2012). "During SNAI1-induced EMT in MCF7 breast cancer cells, miR-203 and miR-200 family members were repressed in a timely correlated manner." (PMID 22514743, 2012). "The SNAI2 and SNAI1 genes have recently been identified as direct transcriptional targets of ATF3 in human mammary cells, and the murine homologs, Snai2 and Snai1 are up-regulated in ATF3-induced mammary tumors." (PMID 21304988, 2011). "In the present study, a 'reverse' analysis was used in breast cancer cells where the activity of SNAI1 had been abolished, with the aim of examining a possible link between SNAI1 and PAI-1 during EMT, a process occurring during tumour progression." (PMID 19055748, 2008). "We compared the invasive breast cancer cell-line MDA-MB-231 expressing SNAI1 (MDA-mock) with its derived clone expressing a dominant-negative form of SNAI1 (SNAI1-DN)." (PMID 19055748, 2008). "In several tumours, including breast cancers, SNAI1 has been correlated with invasive growth potential, partly because of its ability to directly repress transcription of genes whose products are involved in cell-cell adhesion." (PMID 19055748, 2008). "NF-κB increases EMT-associated genes SNAI1, TWIST1, ZEB1, and VIM in a variety of disease processes including pulmonary lung fibrosis and many cancers: head and neck, prostate, pancreatic, and breast cancer." (PMID 39348939, 2024).
breast cancer (continued). "Furthermore, using METABRIC data, we found positive correlations between expression of ZFP36 and genes associated with the stem-like phenotype, as TWIST1, TWIST2, SNAI1, ZEB1, ZEB2, ALDH1A and YAP1 in all breast cancer subtypes." (PMID 38274271, 2023). "While other EMT-related genes (e.g., SNAI1 and VIM) are highly coexpressed, ESR1 (Estrogen Receptor alpha) is one of the top anticorrelated genes, in agreement with the FOSL1-associated mesenchymal features of triple-negative (and basal-like) breast cancers." (PMID 37176013, 2023). "The suppression of SNAI1 expression was observed to result in the altered regulation and expression of several hundred additional genes, resulting in a significant repression of cell motility in breast cancer cells." (PMID 36980876, 2023). "However, other studies have reported a higher expression of SNAI1 in patients with complete pathological response to therapy, postulating a protective and anti-tumorigenic role for SNAI1 in breast cancer." (PMID 36347335, 2023). "In breast cancer, SNAI1 and SNAI2 expression was high, whereas SNAI3 expression was low." (PMID 35898399, 2022). "Another report shows that AR directly represses SNAI1 gene transcription by binding to AR-responsive elements in the SNAI1 promoter in prostate cancer, which is similar to the mechanism we present in this study for breast cancer." (PMID 35605663, 2022). "Similarly, when Snai1-ER was stably expressed in MCF7 human luminal breast cancer cells, AMPK genes were also repressed by 4HT." (PMID 35883651, 2022). "Similarly, in breast cancer, high expression of SNAI1 and/or TWIST1 in tumor-adjacent tissues has been demonstrated." (PMID 36140779, 2022). "LinkedOmics was used to analyze DEGs related with SNAI1 in breast cancer." (PMID 35898399, 2022). "Therefore, we analyzed the published chromatin immunoprecipitation sequencing (ChIP-seq) data of Snai1 in the MMTV-PyMT mammary tumor cells." (PMID 35883651, 2022). "This present evidence may contribute a better understanding of FBXL10 and SNAI1 in metastasis of breast cancer, it may provide a novel therapeutic approach to develop the targeted drugs or inhibitors for the treatment of breast cancer." (PMID 34718323, 2021). "Therefore, our study not only uncovers a role for STK39 in breast cancer progression but also provides new insights into the regulation of SNAI1." (PMID 34335956, 2021). "And it promoted the transcriptional repression activity of SNAI1 on CDH1 in breast cancer cells." (PMID 34718323, 2021). "SNAI1 expression was inversely correlated with tumor-free survival in breast cancer." (PMID 34335956, 2021). "Indeed, we showed that macrophage-mediated phagocytosis was activated by either blocking the EMT-dependent CD47 overexpression via anti-CD47 antibody or silencing of SNAI1 or ZEB1 via siRNA in mesenchymal MDA-MB-231 breast cancer cells." (PMID 33803139, 2021). "In breast cancer cells, SNAI1 recruits G9a to the CDH1 promoter for transcription silencing." (PMID 34681726, 2021). "The western blot and the band intensity analysis hinted that over-expression of TUSC8 down-regulated the expression of mesenchymal related markers (ZEB1, TWIST, SNAI1 and Vimentin) in breast cancer cell lines SK-BR-3 and MDA-MB-435 (p < 0.05, p < 0.01 respectively)." (PMID 32039833, 2020). "Conversely, knock-down of TUSC8 up-regulated the expression of mesenchymal related markers (ZEB1, TWIST, SNAI1 and Vimentin), and down-regulated the expression of epithelial related marker (E-cadherin) in breast cancer cell lines MCF-7 and HCC1937 (p < 0.05, p < 0.01 respectively)." (PMID 32039833, 2020). "It represses EMT breast cancer by inducing the ubiquitination of the Snai1 transcription factor." (PMID 33114139, 2020).
breast cancer (continued). "Consistent with our previous results in chemotherapy-resistant CTCs and MDA-MB-231 breast cancer cell lines, expression of nuclear LSD1p (nLSD1p) and other mesenchymal markers (SNAI1, CD133) was enriched in TNBC xenografts following treatment with Abraxane (nab-paclitaxel) and doxycycline." (PMID 32612611, 2020). "Additional evidence demonstrated that pristimerin increases miR-542-5p levels and that this miRNA directly targets ubiquitin-specific-processing protease 17-like protein 2 (USP17L2, also referred to as DUB3), which promotes migration, invasion, and metastasis of breast cancer by stabilizing SNAI1." (PMID 33066509, 2020). "Hence, it is that low expression levels of SIK1 in breast cancer cells induce the activity and expression of Nav1.5, followed by high expression of SNAI1, triggering the EMT and metastasis observed in breast cancer cells." (PMID 32792949, 2020). "For example, in basal-like breast cancer, SNAI1 represses fructose-1,6-bisphophatase 1 (FBP1), promoting glucose uptake and the diversion of glycolytic carbons towards biosynthetic pathways, including the pentose phosphate pathway (PPP), and impairing the activity of the respiratory chain complex I." (PMID 31277295, 2019). "SETDB1 is known to contribute to the EMT process in breast cancer by interacting with the SMAD/ transforming growth factor-beta (TGF-B) regulatory pathway that influences EMT-inducing transcription factors such as zinc finger protein SNAI1 (Snail-1)." (PMID 31405032, 2019). "To test this hypothesis, we investigated the correlation between a three-gene signature of PAPP-A, COL1A1, and SNAI1 and clinical outcomes in breast cancer patients." (PMID 31046834, 2019). "Additionally, it has been shown that SNAI1/SNAI2 can induce drug resistance in breast cancer cells via alteration of cell survival signaling pathways." (PMID 29921289, 2018). "Moreover, a significant (p < 0.005) correlation between SYNJ2BP and p-AKT was also observed in SNAI1-positive breast cancer tissue samples." (PMID 29163781, 2017). "Moreover, compared with matched primary breast cancer tissues, miR-182 increased in metastatic lymph nodes, while SNAI1 decreased in these lymph nodes." (PMID 27894095, 2017). "We characterized that microRNA-182 (miR-182), which was directly suppressed by SNAI1, could enable an epithelial-like state in breast cancer cells." (PMID 27894095, 2017). "Additionally, we collected 168 pairs of human breast cancer tissue specimens confirmed with positively metastatic lymph nodes, and examined both miR-182 and SNAI1 expression histologically." (PMID 27894095, 2017). "We identified that miR-182, which was directly suppressed by SNAI1, could enable an epithelial-like state in breast cancer cells in vitro, and enhance colonization and macrometastases in vivo." (PMID 27894095, 2017). "ANGPT2 promoted metastasis of breast cancer through SNAI1 induction and E-cadherin inhibition." (PMID 27323831, 2016). "Similarly, breast cancer metastases in an inducible Snai1 expression mouse model are highly dependent on Snai1 expression only when the expression is transient." (PMID 26985909, 2016). "We also analysed the association between DACH1 and E-cadherin levels in SNAI1-positive or -negative breast cancer tissue samples." (PMID 25775416, 2015). "MiR-203 was found to be repressed by SNAI1 during SNAI1-induced EMT in MCF7 breast cancer cells." (PMID 24598126, 2014). "Also increased expression of TWIST1 and SNAI1 in lymph node metastasis (LNM) of early breast cancer patients, reported previously by our group, conferred worse prognosis, confirming the correlation of EMT with aggressive disease behavior." (PMID 24217115, 2013). "In another study, Vetter and coworkers showed that miR-661 expression in MCF7 breast cancer cells conditionally overexpressing the EMT master regulator SNAI1 contributes to breast cancer cell invasion by targeting cell-cell adhesion Nectin-1 and the lipid transferase StarD10 messengers." (PMID 22408395, 2012).
breast cancer (continued). "Moreover, Blanco and colleagues have reported that SNAI1 expression is correlated with both histological grade and lymph node extension in breast cancers." (PMID 19055748, 2008). "This factor up-regulates the expression of PAI-1, uPA and SNAI1 in breast cancer cells." (PMID 19055748, 2008). "Consequently, these compressed breast cancer cells secrete more IL-6 cytokines into the tumour microenvironment where it then functions in autocrine and paracrine manners to upregulate downstream gene targets of IL-6 such as SNAI1." (PMID 40371393, 2025). "Therefore, we hypothesise that the upregulation of SNAI1 protein levels observed in compressed breast cancer cells could be due to the solid stress-induced upregulation of IL-6." (PMID 40371393, 2025). "We identified 7 genes (ITGB1, SNAI1, NOTCH4, STAT5B, RAPGEF3, LAMA2, and GNAI1) that have been implicated in both stemness and the drug response and validated their relevance through an analysis of data from breast cancer patients in the TCGA database using UCSC Xena." (PMID 39180549, 2024). "Thus, we hypothesize that FOXA1-driven AR expression in TNBC-basal SNAI1-mutant cells triggers a transcriptional program reminiscent of ER-mediated transcription in luminal breast cancer, whose exact mechanism awaits further investigation." (PMID 36171192, 2022). "However, the dynamic regulatory network of SNAI1 PTMs during EMT in breast cancer has not been fully illustrated, so more factors associated with modifications of SNAI1 should be identified in cancer progress." (PMID 34718323, 2021). "Meanwhile, the increase in both PlGF and SNAI1 in pCR patients potentially suggests their antitumorigenic role in breast cancer that paves the way for further mechanistic investigation to validate their role as potential predictive markers for pCR in breast cancer." (PMID 31106153, 2019). "In addition, we have observed an increase in protein expression of the transcription factors SNAIL (SNAI2) and SLUG (SNAI1) in progranulin-treated breast cancer cell lines suggesting that progranulin also increase epithelial-mesenchymal transition (EMT) features of breast cancer cells." (PMID 30454027, 2018). "Thus, the down regulation of ZNF703 and SNAI1 by HOXA11 overexpression may contribute to breast cancer suppression." (PMID 28038461, 2017). "In addition, SYNJ2BP was highly expressed in breast carcinoma (p = 0.0031), but not in normal breast tissue, while analysis of tissue samples taken from SNAI1-positive human breast cancers showed a significant correlation between the expression of SYNJ2BP and that of p-AKT (p < 0.005)." (PMID 29163781, 2017). "Moreover, they suggest, that the analysis of breast tissue for PKD-mediated phosphorylation of SNAI1 using our novel phosphoS11-SNAI1-specific antibody may allow predicting the invasive potential of breast cancer cells." (PMID 22276203, 2012). "EMT markers, especially Twist, SNAI1, and E-cadherin, show significant alterations, indicating the activation of EMT pathways in luminal breast cancer." (PMID 40685476, 2025). "It has been reported that in the presence of IL-6 secreted from adipocytes, breast cancer cells (MDA-MB-468 and MCF-7) exhibited enhanced migratory and invasive capacity as a consequence of IL-6 protein and SNAI1 transcription upregulation." (PMID 40371393, 2025). "In breast cancer cells, TRIM21 regulates the EMT process by affecting the proteasomal degradation of SNAI1." (PMID 39154024, 2024). "Immunoblotting of mammary tumour chunks showed dramatic upregulation of HIF1α that was concomitant with increased VIM, SNAI1, TWIST and decreased E-CAD expression in GPx2 KD relative to control tumours." (PMID 38238426, 2024). "It has been reported that BHLHE40 can promote SNAI1 and SNAI2 expression and inhibit the expression of CLDN1, CLDN4, and CDH2 in breast cancer, promoting the migration and invasion of tumor cells." (PMID 37377917, 2023).
breast cancer (continued). "Other studies have reported that miR-153 promotes breast cancer cell apoptosis by targeting HECTD3 and suppresses human laryngeal squamous cell carcinoma migration by targeting the SNAI1 gene." (PMID 37381058, 2023). "Recently, it has been reported that TRPC1 overexpression increases markers for an EMT-like phenotype, such as zinc finger proteins, SNAI1 (SNAIL) and SNAI2 (SLUG), and VIMENTIN, by increasing invasiveness in mouse breast cancer cell lines in vitro." (PMID 37892239, 2023). "ChIP-seq analysis reveals significant overlap between PML-, ER-, and Myc-bound promoters, suggesting their coordinated regulation of target gene expression, including genes involved in breast cancer stem cells (BCSCs), such as JAG1, KLF4, YAP1, SNAI1, and MYC." (PMID 37720048, 2023). "Significant downregulation of the miR-200 family, which consists of miR-141, miR-200a, miR-200b, miR-200c, and miR-429, regulates the expressions of mesenchymal markers ZEB1, ZEB2, TWIST1, TWIST2, Snai1, and Snai2 and promotes EMT in breast cancer." (PMID 37533517, 2022). "Gene expression analyses in breast cancer have reported increased SNAI2 expression in high grade tumors, while SNAI1 showed a reduced expression, similar to our observations in MCF7 cells cultured in PDSs." (PMID 35565301, 2022). "On the contrary, the hMSCs derived from both sources enhanced breast cancer cell migration, possibly by increasing the expression of MYC, SNAI1, and TWIST genes in those cells." (PMID 36406002, 2022). "U-box-type E3 ubiquitin ligase PPIL2 can inhibit EMT and invasion of breast cancer by interacting with the classical EMT transcription factor, SNAI1, to enhance its ubiquitin-dependent degradation." (PMID 36385010, 2022). "The results indicated that SNAI1 and SNAI2 are highly expressed in breast cancer and are positively correlated with poor prognosis." (PMID 35898399, 2022). "In contrast, hMSCs from both sources enhanced breast cancer cell migration, possibly by increasing the expression of MYC, SNAI1, and TWIST genes in those cells." (PMID 36406002, 2022). "On the contrary, hMSCs from both sources enhanced breast cancer cell migration, possibly by increasing the expression of the MYC, SNAI1, and TWIST genes in these cells." (PMID 36406002, 2022). "Recently, ZNF281 was shown to activate epithelial to mesenchymal transition (EMT) transcription factors, ZEB1 and SNAI1 via activation of the TGF-β pathway, promoting EMT and metastasis in breast cancer." (PMID 36207293, 2022). "SNAI1 proteins regulate the immune cells infiltration; however, the relationships between SNAI expression levels and immune cell infiltration in breast cancer are unclear." (PMID 35898399, 2022). "DDR2 was shown to regulate SNAI1 stability through stimulating ERK2 activity and thereby facilitate breast cancer metastasis." (PMID 36713812, 2022). "The stability of SNAI1 mRNA is also enhanced by heterogeneous nuclear ribonucleoprotein, which thus promotes invasion, metastasis, and EMT in breast cancer." (PMID 34681726, 2021). "Herein, we explored the potential role and molecular mechanism of FBXL10 in the invasion and metastasis of breast cancer cells, and evaluated the oncogenic function of FBXL10 and its synergistic effect on SNAI1 in EMT and breast cancer progression." (PMID 34718323, 2021). "Increased TCF8 and SNAI1-induced EMT, which resulted in enhanced migratory and invasive capabilities, was observed in breast cancer cells with ppGalNAc-T4 knockdown." (PMID 33234595, 2021). "The proliferation- and EMT-related proteins including cyclinD1, c-myc, Survivin, Twist, SNAI1, SLUG, ZEB1, E-cadherin, PI3K, p-PI3K, AKT, p-AKT, IKBα, p-IKBα, NF-κB p65, p-NF-κB p65 were detected by western blot in breast cancer cells." (PMID 34419144, 2021). "We examined changes in the expression levels of the EMT-related proteins ZEB1, SNAI1, SLUG, Twist and E-cadherin after AKR1B10-gene intervention in the breast cancer cells by western blot." (PMID 34419144, 2021).